CCNI (cyclin I)
Synonyms: CCNI1; CYC1; CYI
Tractability: PROTAC: ubiquitination databases record sites on it.
Gene: Protein-coding gene on chromosome 4 (77,047,155 to 77,076,319, reverse strand). Ensembl gene ENSG00000118816.
Subcellular location: Nucleus membrane
Subcellular location (Human Protein Atlas): Golgi apparatus; Nuclear bodies; Nucleoplasm
Gene Ontology:
Molecular function: protein binding; cyclin-dependent protein serine/threonine kinase regulator activity
Biological process: spermatogenesis
Cellular component: Golgi apparatus; nuclear membrane; cyclin-dependent protein kinase holoenzyme complex
Genetic constraint (gnomAD): Loss-of-function variants: 7 observed, 22.92 expected, observed/expected ratio (o/e) 0.31, 90% interval 0.17 to 0.57. The upper end of that interval is the gene's LOEUF score, 0.57, which puts it in group 2 of 6, group 1 being the genes least tolerant of losing a copy. Missense variants: 354 observed, 421.3 expected, observed/expected ratio (o/e) 0.84, 90% interval 0.77 to 0.92. Synonymous variants: 145 observed, 155.05 expected, observed/expected ratio (o/e) 0.94, 90% interval 0.82 to 1.07.
Homologues: Orthologues: chimpanzee CCNI (99% identical), dog CCNI (97% identical), pig CCNI (95% identical), guinea pig CCNI (95% identical), mouse Ccni (94% identical), macaque CCNI (93% identical), rat Ccni (87% identical), tropical clawed frog ccni (60% identical), zebrafish ccni (53% identical), Caenorhabditis elegans cyd-1 (16% identical), Caenorhabditis elegans cye-1 (15% identical), Drosophila melanogaster CycE (15% identical), and 5 more. Paralogues in human: CCNI2 (30% identical), CCNG2 (26% identical), CCNG1 (21% identical), CCNE2 (18% identical), CCNE1 (17% identical), CCNJ (17% identical), CCNA2 (16% identical), CCND3 (16% identical), CCNB1 (16% identical), CCNJL (16% identical), CCNB2 (15% identical), CCNA1 (15% identical), and 6 more.
Diseases named in the same sentence as CCNI in open-access papers:
CCNI is named in the same sentence as 22 diseases in open-access papers, as found by Europe PMC text mining. Sharing a sentence is not in itself a finding about the gene and the disease. The quoted sentences say what the papers report.
lung carcinoma (5 papers, 2017 to 2023). "Accordingly, CCNI overexpression was associated with a worse prognosis in patients with lung adenocarcinoma and it was proposed that CCNI mRNA in saliva could be a biomarker for lung cancer detection." (PMID 31420702, 2020). "Indeed, our group has demonstrated that CCNI is overexpressed in lung cancer patients and it is associated with a worse clinical prognosis, while others have reported that salivary CCNI mRNA could be used to discriminate lung cancer patients from normal subjects." (PMID 37081792, 2023). "The non-invasive and affordable diagnosis of lung cancer can beaided by salivary mRNA biomarkers (CCNI, EGFR, FGF19, FRS2, and GREB1)." (PMID 37693919, 2022). "CCNI has also been shown to increase the proliferation of Hela and lung cancer cell lines, although it is still unclear whether these effects are mediated through the interaction with a CDK." (PMID 31420702, 2020). "Given the variability in lung cancers, it is plausible that CCNI may have a relevant role in some lung cancer subtypes; indeed, the two adenocarcinoma cell lines analyzed display significant differences regarding CCNI expression relative to normal human fibroblasts." (PMID 28860486, 2017). "Median protein expression of CCNY, CCNO, CCNI, and CNTD2 was higher in lung cancer than normal lung tissue, but statistical significance was only found for CCNI and CNTD2." (PMID 28860486, 2017). "The logistic regression model combining the five mRNA biomarkers (CCNI, EGFR, FGF19, FRS2, and GREB1) can distinguish patients with lung cancer from normal controls (area under the receiver operating characteristic curve [AUC-ROC] = 0.925; sensitivity = 93.75%; specificity = 82.81%)." (PMID 35651679, 2022). "Confirming the results obtained of Western analysis, examining six pairs of lung cancer and paired adjacent normal tissue by immunohistochemistry demonstrated positive staining for CNTD2, CCNO and CCNI while adjacent normal lung was generally negative." (PMID 28860486, 2017).
melanoma (5 papers, 2018 to 2022). A malignant, usually aggressive tumor composed of atypical, neoplastic melanocytes. "Edited CCNI has been reported to be a candidate neoantigen induced by RNA editing in melanoma and a target of immunotherapy." (PMID 35941214, 2022). "We synthesised edited CCNI peptides and their wildtype counterparts and evaluated their ability to activate TILs generated from human melanoma tumours." (PMID 30254248, 2018). "Among them, ADAR1 edited cyclin I (CCNI)R75G peptides were characterized to activate tumor infiltrating lymphocytes (TIL) generated from human melanoma tumors." (PMID 30585209, 2018). "Focusing on the HLA-A ligands found for an ADAR1 editing site of cyclin I (CCNI R75G), the authors showed that edited CCNI peptides activated tumor-infiltrating lymphocytes from human melanoma tumors, suggesting edited CCNI peptides function as antigenic epitopes in vivo." (PMID 32650588, 2020). "Based on the established correlation between edited mRNA and peptide, we performed RNA-sequencing analyses to detect CCNI mRNA editing in melanoma cell lines, including mel-2661, mel-2559 and mel-2400 derived from the patients used for generating TIL2661 and TIL2559." (PMID 30254248, 2018). "This phenomenon was recently shown in melanoma, where TILs were able to recognize the peptides derived from the ADAR1-edited form of cyclin I (CCNI) presented on the surface of cancer cells." (PMID 35634292, 2022).
breast carcinoma (2 papers, 2023 to 2025). "We grouped breast cancer patients with the lowest and highest quarters of CCNI expression and we found that CCNI was significantly linked to the expression of several E2F‐regulated genes in breast cancer patients." (PMID 37081792, 2023). "CCNI upregulation increased the proliferation of breast cancer cells in vitro and in vivo, with a magnitude similar to that seen upon cyclin D upregulation, an effect that was abrogated by CDK6 silencing or palbociclib treatment." (PMID 37081792, 2023). "Our results show that, by interacting with CDK6, CCNI promotes the proliferation of breast cancer cell lines, unraveling a new pathway that contributes to cell cycle regulation and tumorigenesis." (PMID 37081792, 2023). "Finally, CCNI upregulation correlated with the high expression of E2F target genes in large panels of cancer cell lines and tissue samples from breast cancer patients." (PMID 37081792, 2023). "To investigate the effect of CCNI expression in vivo, we selected MDA‐MD‐231 cells, a model of triple‐negative breast cancer, which has a poorer prognosis as compared to other breast cancer types." (PMID 37081792, 2023). "The transcriptome biomarker profile, which includes the leucine zipper putative tumor suppressor 1, fibroblast growth factor receptor substrate 2, cyclin I, the EGF receptor, FGF-19, B-Raf gene, and growth regulation by estrogen in breast cancer 1, has been identified." (PMID 41245374, 2025). "Interestingly, we show that the effects of CCNI on the growth of animal models of triple‐negative breast cancer are similar to the ones promoted by CCND1, the deregulation of which is a breast cancer hallmark." (PMID 37081792, 2023).
cervical cancer (1 paper, 2025). A primary or metastatic malignant neoplasm involving the cervix. "A notable example is found in cervical cancer, where resistance to the chemotherapeutic agent cisplatin is driven by the upregulation of Cyclin I. In this context, the Cyclin I-Cdk5 complex functions as a critical anti-apoptotic factor, protecting cancer cells from drug-induced cell death." (PMID 41369365, 2025).
gastric cancer (1 paper, 2023). A primary or metastatic malignant neoplasm involving the stomach. "Among the top de-regulated genes (absolute log fold change above 0.5 and Wilcoxon test p-values below 0.01) we found CCNI, which is involved in the induction of angiogenesis and whose up-regulation was correlated with lymph-node metastases in gastric cancer." (PMID 37917660, 2023).
nephritis (1 paper, 2021). Inflammation of renal tissue. "In contrast, following podocyte stress in the nephrotoxic nephritis model (NTN), apoptosis was higher in the p35/cyclin I double knockout mice compared to a similar stress in the single p35 or cyclin I null mice." (PMID 34572114, 2021).
pancreatic cancer (1 paper, 2024). "This study aims to explore the role of cyclin I-like protein (CCNI2), a homolog of cyclin I (CCNI), in the progression of pancreatic cancer, thereby providing a theoretical basis for its treatment." (PMID 37540586, 2024).
renal clear cell carcinoma (1 paper, 2023). "Depending on the histological type, CCNI may be associated with either a better (sarcoma, breast) or worse (renal clear cell carcinoma, ovarian) clinical prognosis." (PMID 37081792, 2023).
tumor (11 papers, 2017 to 2023). "MDA‐MD‐231 cells overexpressing CCNI formed significantly faster‐growing tumors than control, supporting that CCNI, when overexpressed, contributes to enhance tumor growth." (PMID 37081792, 2023). "Having established the correlation between edited peptide and mRNA, we used TCGA tumour data to extend our mechanistic understanding of CCNI editing." (PMID 30254248, 2018). "The identification of CCNI-ED as an antigen able to activate human T cells prompted us to determine the function of CCNI-ED specific T cells in mediating tumour cell killing." (PMID 30254248, 2018). "We report the in-depth characterisation of an editing site of cyclin I (CCNI R75G) with regard to peptide presentation, T-cell recognition and tumour association." (PMID 30254248, 2018). "Presentations of these edited peptides, such as cyclin I (CCNI; R75G), elicit antigen-specific killing of tumor cells through cytotoxic (CD8+) T cells." (PMID 30619092, 2018). "We provide evidence that effector CD8+ T cells specific for edited peptides derived from cyclin I are present in human tumours and attack tumour cells that are presenting these epitopes." (PMID 30254248, 2018). "CNTD2 was predominantly localized to the nuclei of tumor cells, while the CCNI localized to the nuclear membrane and CCNO appeared concentrated in nucleoli." (PMID 28860486, 2017). "The prognostic significance of CCNI within the same tumor type may also depend on smoking or alcohol consumption." (PMID 37081792, 2023). "Given the multiple contexts that may be found in the highly heterogeneous tumor environment, a better understanding of CCNI regulation will be critical to unveil the full significance of the CCNI and CCND1 interplay." (PMID 37081792, 2023). "Indeed, we were able to detect endogenously edited CCNI mRNA except for mel-2559, which was derived from the same patient as mel-2400 yet from a different tumour sample." (PMID 30254248, 2018). "Thus, we focused on the HLA-A*02 ligands found for CCNI for in-depth characterisation making use of quantitative HLA-A*02 peptidome data for 925 samples covering tumour (n = 504) and normal tissues (n = 421)." (PMID 30254248, 2018). "Both CCNI-WT peptides were detected in almost all A*02 positive samples, showing similar levels in normal and cancer tissues.While CCNI-ED was also presented on healthy tissues, it showed elevated abundances in several tumours." (PMID 30254248, 2018). "The frequent over-editing of Cyclin I (CCNI) by ADAR1 in OC was found to produce peptide products that activate T-cell responses and specifically kill tumor cells." (PMID 35964092, 2022). "The authors found that the cell cycle kinase CDK6 forms an active complex with the atypical cyclin I (CCNI) and that this complex promotes retinoblastoma phosphorylation, E2F‐mediated gene expression, and tumor proliferation in vitro and in vivo, similarly to the cyclin D1 (CCND1)/CDK6 complex." (PMID 37081792, 2023). "Interestingly, CDK5 was also shown to be activated by binding to cyclin I in cisplatin-resistant cervical cancer cells, where cyclin I–CDK5 complex was proposed to protect tumour cells from apoptosis." (PMID 31910742, 2020). "IFNγ ELISPOT assays detected strong reactivity of Ted10 to mel-2400 and mel-2661 as well as another CCNI-editing positive tumour line, mel-2391, whereas Ted10 cells displayed only a background level response to the CCNI-editing negative mel-2559." (PMID 30254248, 2018). "Moreover, CCNIR75G peptides, but not wild type CCNI, facilitates TIL mediated tumor cell killing." (PMID 30585209, 2018).
cancer (10 papers, 2017 to 2025). A tumor composed of atypical neoplastic, often pleomorphic cells that invade other tissues. "The CDK‐binding‐deficient form of CCNI was unable to increase cell proliferation, in contrast to the wild‐type form, suggesting that CCNI stimulates cancer cell proliferation through the interaction with a CDK." (PMID 37081792, 2023). "Furthermore, these observations support that CCNI is implicated in cancer progression and has the potential to become a biomarker for patient stratification." (PMID 37081792, 2023). "We show that CCNI activates CDK6 to increase cancer cell proliferation via pRb phosphorylation, suggesting that CCNI is another piece in the cell cycle machinery puzzle and a new potential oncogenic driver." (PMID 37081792, 2023). "We preferred to use overexpression to better mimic a subset of human cancers that present CCNI upregulation." (PMID 37081792, 2023). "We then investigated the effect of CCNI downregulation on two pRb phosphorylation sites in cancer cell lines in which the pRb checkpoint is active." (PMID 37081792, 2023). "In particular, CCNI-edited peptides act as cancer antigens capable of activating tumor infiltrating lymphocytes (TILs) and thereby mediate cancer cell death in melanoma." (PMID 33445472, 2021). "Moreover, editing events of these genes have been associated with cancer progression (e.g., AZIN1, COPA, CCNI, and FLNB) or neurological disorders (e.g., GRIK2 and GRIA2–4)." (PMID 35406793, 2022). "CCNI RNA editing induced by CRT may therefore represent a new method by which epigenetic diversity can be controlled for the purpose of cancer immunotherapy." (PMID 35941214, 2022). "Moreover, the analysis of the overall survival of cancer patients stratified by CCNI expression level suggests that this cyclin may have prognostic significance in cancer." (PMID 37081792, 2023). "Finally, we investigated CCNI expression in human cancer in UCSC Xena." (PMID 37081792, 2023). "Accordingly, it has been demonstrated that in HeLa cells overexpressing cyclin I, the activation of CDK5 by cyclin I confers cancer cell resistance to CP, while knockdown of CDK5 with siRNA significantly increases the sensitivity to CP." (PMID 38474332, 2024).
CCNI also shares sentences with these, for which no sentence is quoted: lung adenocarcinoma (2 papers); acute myeloid leukemia (1); adenocarcinoma (1); colorectal cancer (1); epithelial ovarian cancer (1); glomerulosclerosis (1); neurological disorders (1); ovarian cancer (1); pancreatic ductal adenocarcinoma (1); rheumatoid arthritis (1); sarcoma (1); ZTTK syndrome (1).